ALB (albumin)
Diseases named in the same sentence as ALB in open-access papers (continued):
Sharing a sentence is not in itself a finding about the gene and the disease.
hemorrhage (26 papers, 2008 to 2026). Loss of blood from the vascular compartment to the exterior or into nonvascular body space as a result of rupture or severance of the blood vessels. "Here, these experiments are extended to a hemorrhage experiment, in which Hr polymerized with glutaraldehyde, alone or conjugated with human serum albumin, is administered after a loss of 20–30% blood volume." (PMID 36620348, 2022). "In postpartum women, nutritional demands increase, and parturients undergoing cesarean section or experiencing significant hemorrhage are more likely to have decreased albumin levels." (PMID 40520340, 2025). "Study 3 reported changes in four outputs (HR, MAP, cardiac index, and SvO2) across three distinct experimental groups, with each group using a different resuscitation fluid type (NS, HTS, or Albumin + HTS) following hemorrhage." (PMID 40666119, 2025). "Decreased calcium and albumin (PED 4–5 through termination) are suggestive of hemorrhage, as calcium is a key cofactor in the coagulation cascade and is involved in platelet function." (PMID 34214118, 2021). "We found that ALB, PT, GP73 and C-P scores were all associated with hemorrhage in cirrhotic patients with EVs." (PMID 34926512, 2021). "For HT, more patients were found with low level of albumin (15.3% vs. 4.2%, P = 0.002), and the incidence of symptomatic hemorrhage was different between two groups (6.2% vs. 1.4%, P = 0.03)." (PMID 28798356, 2017). "PEG-albumin treatment yielded higher functional capillary density during the initial stages of hemorrhage as compared with HES treatment." (PMID 18423033, 2008). "The measured HA concentration could have been normalized to albumin concentration or hematocrit to address this, however these parameters are also likely to change due to hemorrhage and critical illness and not only hemodilution." (PMID 40512747, 2025). "From the results of the best algorithm models with different outcomes, it is known that the most important risk factors are: Ccr, ALB, CHA_2DS_2-VACs, DD, AST, NT-pro-BNP, LDH, TSH, CREA, age, UA, DBP, and LAD for any complication, cardiac effusion/tamponade or hemorrhage." (PMID 37950179, 2023). "In addition, the results of this study suggest that antepartum albumin and EFW of twins were risk factors for postpartum hemorrhage in twin pregnancies." (PMID 37144027, 2023). "Maintenance of a greater mean arterial pressure during the initial stages of hemorrhage is proposed to be in part due to the improved volume expansion with PEG-albumin, as indicated by the significant decrease in systemic hematocrit compared with the HES group." (PMID 18423033, 2008). "The five confirmed predictors were hemorrhage volume, Glasgow Coma Scale (GCS) score, surgery time, albumin, and glucose." (PMID 41658585, 2026). "The Glasgow Coma Scale (GCS) score, intraventricular extension of hemorrhage (ICH with IVH), surgeries, albumin, and distance to the midline were identified as significant predictors of GIB in patients with sICH." (PMID 41551318, 2025). "In addition, k was split into two elimination functions that were governed by two rate constants, kb and kbleed, which separated the unknown losses of intravascular albumin by transcapillary leakage from the known losses of albumin by hemorrhage and blood sampling." (PMID 35410365, 2022). "Though other parameters like hemorrhage and increased BALF albumin concentrations suggest changes to the permeability of the alveolar–capillary barrier, this is a limitation of the present model." (PMID 33870468, 2021). "The results show that the PVE power of the fluids differed greatly: The PVE power was 0.18 for RL, 0.73 for 5% albumin, and 2.09 for 20% albumin, confirming our primary hypothesis that 20% albumin has the strongest PVE effect as a fluid therapy during hemorrhage." (PMID 38317178, 2024).
Portal vein thrombosis (26 papers, 2010 to 2026). Thrombosis of the portal vein and/or its tributaries, which include the splenic vein and the superior and inferior mesenteric veins. "Univariate and multivariate regression analyses (including COX and logistic) identified male gender, portal vein thrombosis, and low albumin levels as independent risk factors for postoperative rebleeding." (PMID 39981811, 2025). "We conducted a univariate Cox regression to assess the impact of factors like transcriptomic signature, performance status, liver transplant, BCLC stage, albumin, CRP, nodule count, and portal vein thrombosis on survival, all showing significant associations." (PMID 39456643, 2024). "A randomized controlled trial conducted by Zhou et demonstrated that the Child-Pugh score and albumin level of cirrhotic patients with portal vein thrombosis were increased after six months of warfarin treatment." (PMID 36631860, 2023). "We found that blood albumin levels and the presence of portal vein thrombosis (PVT) and tumor multifocality all had hazard ratios ≥2.0." (PMID 33546234, 2021). "In univariate Cox proportional hazards analysis, we found that age, LC, TB, DB, ALB, AST, alkaline phosphatase, γ-GT, PT, PTA, white blood cell count, number of tumor nodules, portal vein thrombosis and MVI were significantly associated with mortality (all P < 0.05)." (PMID 26057656, 2015). "We evaluated the role of baseline laboratory values, such as albumin, bilirubin, Alpha fetoprotein (AFP), Portal vein thrombosis (PVT), etc. as significant factors for predicting OS." (PMID 38981950, 2024).
alcoholism (25 papers, 2012 to 2025). "Levels of albumin were negatively associated with alcohol dependence, but the corresponding genetic correlation was null." (PMID 40766921, 2025). "Findings suggest that shared genetic effects may contribute to positive associations of alcohol consumption with albumin in both sexes, as well as positive associations between alcohol consumption and bioavailable testosterone and between alcohol dependence and SHBG in males." (PMID 38464231, 2024). "These clinical findings further implied the tumour promotion effect of the ALB+KRT7+ epithelial cells in alcohol‐related HCC." (PMID 39834100, 2025). "Coherently, we observed more immunosuppressive‐like tumour environment in alcohol‐related HCC with high ALB+KRT7+ population abundance." (PMID 39834100, 2025). "Using UK Biobank data, we observed higher total testosterone and SHBG levels, but lower albumin levels, in both males and females with alcohol dependence history." (PMID 40766921, 2025). "Recently we described associations of alcohol consumption and alcohol dependence with testosterone, estradiol, SHBG, and albumin in data from the UK Biobank, with striking differences by sex14." (PMID 38464231, 2024). "The incidence of RFS in neurocritical patients was high, and history of alcoholism, fasting hours, APACHE II scores, SOFA scores, low serum albumin, and low baseline serum potassium were the main risk factors for RFS in neurocritical patients." (PMID 36875840, 2023). "Logistic regression analyses showed that six factors were associated with RFS, including history of alcoholism, fasting hours, APACHE II scores, SOFA scores, serum albumin, and baseline serum potassium." (PMID 36875840, 2023). "Shared genetic effects may contribute to the positive relationship between alcohol consumption and levels of albumin in both sexes, and between alcohol dependence and levels of BMI-adjusted SHBG in males." (PMID 40766921, 2025). "Levels of albumin were negatively associated with alcohol dependence but did not have any corresponding genetic correlation." (PMID 38464231, 2024). "Univariate survival analysis show that DM, age, gender, HBV, alcoholism, albumin, bilirubin, INR, Na, AFP, eGFR, variceal bleeding, total tumor volume, vascular invasion, presence of ascites, and platelet count were significant predictors for survival in HCC patients (all p< 0.05)." (PMID 28333991, 2017). "Alcohol dependence was not genetically correlated with albumin in males and females (rg = 0.005, p = 0.91)." (PMID 40766921, 2025). "Alcohol dependence was not genetically correlated with albumin in males and females (rg = 0.0054, p = 0.9110)." (PMID 38464231, 2024). "Based on univariate and binary logistic regression analyses, six independent risk factors for RFS in neurocritical patients were ultimately obtained, including a history of alcoholism, fasting hours, APACHE II scores, SOFA scores, serum albumin, and baseline serum potassium." (PMID 36875840, 2023).
amyloidosis (25 papers, 2010 to 2025). A disorder characterized by the localized or diffuse accumulation of amyloid protein in various anatomic sites. "It is noteworthy that non‐amyloidosis‐associated proteins reported in human cases of AApoAIV amyloidosis such as vitronectin, serum albumin, clusterin, collagen alpha‐2 (I) chain, collagen alpha‐1 (I) chain, and actin 48 were also found in our samples." (PMID 29774542, 2018). "On the other hand, significant amount of albumin in urine is frequently associated with amyloidosis or MIDD." (PMID 24877060, 2014). "SRA proteins transthyretin, complement C3, albumin, fibrinogen, α-2-macroglobulin, fibronectin 1, and α-1-antitrypsin have been related to amyloidosis." (PMID 37902886, 2024). "The AG ratio was lowest in LCCN in this regard studies have mentioned only serum albumin which was lowest in amyloidosis." (PMID 36699747, 2023). "Although the TTR concentrations were negligible in the healthy volunteers, they were correlated with disease progression and urinary albumin concentrations in the ATTRv V50M amyloidosis patients." (PMID 35893595, 2022). "The correlation of TTR concentrations in urine versus the ATTRv score, even in patients at early-stage ATTRv amyloidosis, is much stronger than that of the albumin concentrations and creatinine levels." (PMID 35893595, 2022). "No statistical differences were shown in the aspect of gender, disease stages, accompanied cytogenetics, hemoglobin, calcium, lactate dehydrogenase (LDH), albumin, β2-microglobulin and amyloidosis between the two groups." (PMID 36531062, 2022). "The FMD percentage and albumin levels were significantly lower in the FMF-related amyloidosis group (p < 0.001 and p = 0.001 respectively)." (PMID 33110219, 2020). "Many cases of amyloidosis are characterized by kidney involvement, which is defined as 24-hour urinary protein, mostly albumin, exceeding 0.5 g." (PMID 25657979, 2015). "Also they have reported proteinuria, and serum albumin and serum creatinine levels were correlated with degree of amyloidosis." (PMID 27590627, 2016). "Here, the authors show that a decrease in serum albumin levels in long-term dialysis deteriorates the inhibitory effects of serum milieux on supersaturation-limited amyloid formation of β2m, suggesting that macromolecular crowding protects the onset of amyloidosis." (PMID 36192385, 2022). "The group validated their findings using an additional model of amyloidosis, namely 5xFAD mice transduced with AAV-albumin-ApoE3 or AAV-albumin-ApoE4, to determine how peripheral ApoE isoforms affect amyloid pathology in the presence of brain ApoE." (PMID 36195891, 2022). "Prolongation of prothrombin time coexisted with amyloid infiltration of the liver, proteinuria, and decreased serum albumin, while thrombin time extension was independent of the total amount of amyloid determined by SAP scintigraphy." (PMID 35207184, 2022). "Amyloidosis was diagnosed in 59.5% of patients with MGRS, which is consistent with the findings of previous studies and may explain the lower albumin level and worse podocyte effacement in MGRS group than the other groups." (PMID 34217367, 2021).
endotoxemia (25 papers, 2008 to 2025). "Animal experiments have shown that albumin can counteract the decline in arterial vascular reactivity caused by endotoxemia, alleviate ischemia-reperfusion injury, and possess anti-inflammatory effects." (PMID 39699941, 2024). "Endotoxemia was associated with decreased serum albumin and total protein levels, with activated neutrophils, while the glycocalyx glycosaminoglycan hyaluronan was significantly increased in BAL." (PMID 30466423, 2018). "In this study, microarray and Western blot, and so forth, analyses were employed to reveal the key molecular mechanisms for CQCQD decoction in alleviating the pulmonary albumin leakage caused by endotoxemia in SAP rats." (PMID 27413385, 2016). "Moreover, the reversal of the enhanced pulmonary albumin leak should be considered as the therapeutic goal for ALI caused by endotoxemia in SAP." (PMID 27413385, 2016). "Inflammatory factors damage the intestinal epithelium, increase permeability, trigger endotoxemia, further inhibit albumin synthesis and exacerbate inflammation." (PMID 41311510, 2025). "In a model of rat endotoxemia, infusions of 4% or 20% albumin reached higher values of skeletal muscle perfused vascular density and red blood cell velocity than 0.9% NaCl." (PMID 41247634, 2025). "Polymerized albumin was superior to albumin to restore macro and microcirculation, and to prolong survival in experimental models of endotoxemia in mice and of fecal peritonitis in hamsters." (PMID 41247634, 2025). "Animal experiments have shown that serum albumin can act as an antioxidant, reducing arterial reactivity induced by endotoxemia and enhancing anti-inflammatory effects." (PMID 37580693, 2023). "We also found numerous associations between reduced liver function, as measured by plasma albumin levels, and T cell exhaustion/senescence, inflammation, and endotoxemia." (PMID 37626844, 2023). "Among BMI categories, i.e. underweight or normal weight, overweight, and obese, significant differences were found in associations of endotoxemia with large VLDL particles and their lipid content, IDL lipid content, albumin, and omega-3 FAs." (PMID 33243051, 2021). "In animal experiments, serum albumin was shown to be protective through reducing arterial reactivity in endotoxemia as an antioxidant and improving the anti‐inflammatory effect." (PMID 34041866, 2021). "We used an established mouse model of lethal endotoxemia by intraperitoneal injection of Escherichia coli LPS (40 mg/kg) followed by treatment with 100 U/kg PC or control solution (human albumin (8 mg/mL)) after 0.5, 8, and 24 hours." (PMID 24876676, 2014). "High levels of TNF-α were found in serum and lung in rats with endotoxemia, and more albumin was present in endotoxemic lungs than in control ones." (PMID 23671873, 2013). "Indeed, endotoxemia-induced myocardial edema and albumin leakage persisted despite canagliflozin treatment in e-AMPK KO animals." (PMID 34211080, 2021). "ET-R, dominated by Asteroleplasma and Succinivibrio, genera linked to endotoxemia and poor prognosis, is predominant in RHCC patients and is associated with impaired liver function, as reflected by elevated ALT and AST levels, increased total bilirubin, and reduced albumin." (PMID 41239524, 2025). "We measured relationships between liver health (plasma levels of albumin, alanine transaminase (ALT), aspartate transaminase (AST), and transient elastography (TE) score and indices of endotoxemia, inflammation, and T cell exhaustion/senescence." (PMID 37626844, 2023). "Consequently, we speculated that the treatment of CQCQD decoction in the patients with SAP endotoxemia-induced ALI could potentially ameliorate pulmonary albumin leak via depressing the inflammatory cascade reaction and alleviating the damage to cell-cell junction." (PMID 27413385, 2016).
endotoxemia (continued). "Major differences of DIALIVE system compared with MARS and Prometheus are that albumin removed is not recirculated in DIALIVE with wasted albumin replaced by bottled albumin, and the additional endotoxin filter in the DIALIVE system addresses endotoxemia by removing (adsorbing) endotoxins." (PMID 38101419, 2023). "At concentrations as low as 2.5 g albumin/dl, PEG-albumin (carrying 10 copies of PEG-5,000 chains per molecule) is better able to resuscitate from induced endotoxemia, thus preventing the development of circulatory collapse, as compared with 6 g/dl dextran 70 (molecular weight 70 kDa)." (PMID 18423033, 2008). "Albumin is known as a negative APP characterized by decreasing concentrations during an acute phase reaction as a result of decreased hepatic albumin synthesis or extravasation due to endotoxemia." (PMID 38962710, 2024).
glomerulopathy (25 papers, 2011 to 2025).